KEAP1 (kelch like ECH associated protein 1)
Diseases named in the same sentence as KEAP1 in open-access papers (continued):
Sharing a sentence is not in itself a finding about the gene and the disease.
gastric cancer (continued). "A study at the First Hospital of China Medical University showed that ATF3 promotes ferroptosis by inhibiting the Keap1-Nrf2 axis, thereby increasing the sensitivity of gastric cancer cells to cisplatin." (PMID 36038533, 2022). "Similar results were reported in breast and gastric cancer cells, where it was seen that Nrf2/Keap1 promoted cell migration by upregulating the RhoA/ROCK1 pathway." (PMID 33441941, 2021). "As increased nuclear levels of NRF2 protein have been documented in gastric cancer cell lines and tissues, but the frequency of somatic mutations in NFE2L2, KEAP1 and CUL3 is low, it is likely that NRF2 can be upregulated by other mechanisms in GC." (PMID 33276631, 2020). "The implication of Keap1 and its correlation with prognosis of patients with gastric cancer has been observed." (PMID 30811526, 2019). "In our present study, we identified Keap1 as a tumor-suppressor gene which is correlated with better survival of gastric cancer patients." (PMID 30811526, 2019). "Combined with the previous results, it was shown that inhibiting NEK2 could promote the expression of HMOX1 through Keap1/Nrf2, enhance the ferroptosis sensitivity of gastric cancer cells, and further affect the cell biological function." (PMID 38503948, 2025). "Similarly, ATF3 is implicated in ferroptosis induction via inhibition of the Nrf2/Keap1/xCT pathway, which enhances cisplatin sensitivity in gastric cancer cells." (PMID 40115255, 2025). "This research explores the prognostic signature of MAGED2, KEAP1, GLA, EIF1AD, and EHF genes associated with hypoxia in gastric cancer through analyzing transcriptome information and scRNA-seq data, and indicates the clinical relevance of hypoxia during gastric cancer progression." (PMID 40129974, 2025). "Similarly, BDH2 facilitates the ubiquitination of Nrf2 by enhancing the interaction between Keap1 and Nrf2 in gastric cancer, leading to increased ROS accumulation, activation of cellular autophagy, and inhibition of gastric cancer progression." (PMID 39664581, 2024). "Consequently, p62 competitively binds to Keap1, leading to the release of Nrf2 and its translocation to the nucleus, thereby promoting the expression of downstream Nrf2 target genes and enhancing gastric cancer cell survival." (PMID 39664581, 2024). "Activation of the KEAP1/NRF2/HO-1 pathway may be triggered in ferroptosis of gastric cancer cells mediated by ferritinophagy." (PMID 39061086, 2024). "FAM117B promotes the growth of gastric cancer cells via regulation of KEAP1/NRF2 signaling." (PMID 36719368, 2023). "FAM117B activates KEAP1/NRF2 signaling in gastric cancer cells." (PMID 36719368, 2023). "ATF3 (activating transcription factor 3) may induce ferroptosis by blocking the Nrf2/Keap1/xCT signaling pathway and reverse the sensitivity of gastric cancer cells to cisplatin." (PMID 35847022, 2022). "TCF7L1 was negatively correlated with KEAP1 expression in gastric cancer patients." (PMID 30811526, 2019). "However, the expression status of Keap1 in gastric cancer has seldom been discussed in gastric cancer patients." (PMID 30811526, 2019). "Answers to this issue might establish a novel TCF7L1/Keap1/NRF2 axis in gastric cancer malignancy regulation." (PMID 30811526, 2019). "The ChIP assay results showed that TCF7L1 could occupy the promoter region of Keap1 in gastric cancer cells." (PMID 30811526, 2019). "Next, we assessed the contribution of Keap1 expression to gastric cancer prognosis." (PMID 30811526, 2019). "We then investigated whether FAM117B regulates KEAP1/NRF2 signaling in gastric cancer cells." (PMID 36719368, 2023). "MiR-25, miR-141 and miR-223, which are significantly up-regulated in SGC-7901/DDP resistant gastric cancer cells, could enhance DDP resistance via suppressing expression levels of FOXO3a, kelch-like ECH-associated protein-1(KEAP1) and F-Box and WD repeat domain containing 7 (FBXW7), respectively." (PMID 32192494, 2020).
gastric cancer (continued). "In gastric cancer, overexpressed fibroblast growth factor receptor 4 (FGFR4) forms a complex with p62 and KEAP1, which blocks KEAP1-mediated NRF2 ubiquitination and degradation." (PMID 40227215, 2025). "In cisplatin-resistant gastric cancer, elevated ATF3 expression cooperates with erastin to inhibit the Keap1-Nrf2-xCT pathway, thereby promoting ferroptosis in cancer cells and reversing cisplatin resistance." (PMID 39744125, 2024). "Iron ions induce iron-induced cell death and can alter the drug resistance of gastric cancer cells through pathways such as KEAP1/NRF2, STAT3, and Nrf2/Keap1/xCT." (PMID 38370477, 2024). "In this study, we found that FAM117B disrupted KEAP1-NRF2 interaction through its ETGE motif, which reduced the degradation of NRF2 and activated KEAP1/NRF2 signaling, and ultimately promoted the growth and chemoresistance of gastric cancer cells." (PMID 36719368, 2023). "The ETGE motif of FAM117B activates KEAP1/NRF2 signaling and promotes the growth and chemoresistance of gastric cancer cells." (PMID 36719368, 2023). "Previous studies have shown that the KEAP1/NRF2 signaling pathway affects the growth and chemoresistance of gastric cancer cells." (PMID 36719368, 2023). "Another study showed that silencing SIRT6 induced ferroptosis in gastric cancer cells by inducing inactivation of Keap1-Nrf2 and low expression of GPX4, thereby improving the sensitivity of gastric cancer cells to sorafenib." (PMID 36038533, 2022). "We hypothesized that the higher protein level of FAM117B in gastric cancer could compensate for the lower affinity between FAM117B and KEAP1." (PMID 36719368, 2023). "Our findings revealed that FAM117B could bind KEAP1 to upregulate NRF2, then attenuated the sensitivity of gastric cancer to chemotherapeutic drugs." (PMID 36719368, 2023). "The higher protein level of FAM117B in gastric cancer could compensate for the lower affinity between FAM117B and KEAP1." (PMID 36719368, 2023). "To verify the in vitro observations of the negative correlation between TCF7L1 with Keap1, we performed TCGA dataset analysis of their correlation in gastric cancer patients." (PMID 30811526, 2019). "Mechanistic studies demonstrated that TCF7L1 could negatively regulate Keap1 expression and the resultant NRFF2 stability, which positively regulates redox balance and aerobic glycolysis that promote proliferation of gastric cancer cells in patients." (PMID 30811526, 2019). "Therefore, it was not surprising that FAM117B competed with NRF2 to bind KEAP1 in gastric cancer cells, changed the conformation of the KEAP1/NRF2 complex, and inhibited the ubiquitination degradation of NRF2." (PMID 36719368, 2023). "However, we did not examine the epigenetic impacts of TCF7L1 on Keap1 expression, which prompted us to perform further investigations to screen TCF7L1-interacting epigenetic partners in gastric cancer." (PMID 30811526, 2019).
atherosclerosis (30 papers, 2015 to 2026). A disease characterized by the build-up of fatty material and calcium deposition in the arterial wall resulting in partial or complete occlusion of the arterial lumen. "KEAP1-R483S mutation also limited the protective effect of MCL on atherosclerosis progress and macrophage ferroptosis in ApoE−/− mice." (PMID 38100883, 2024). "Our findings provide insight into the Nrf2/Keap1 system and recommend it as a potential therapeutic target to reduce the effects of postangioplasty restenosis and atherosclerosis, which are associated with oxidative stress." (PMID 27198574, 2016). "Since the HFD mouse study focuses on the antioxidant effect of metformin on cardiac tissue, further research on the Nrf2/Keap1-associated antioxidant effect of metformin on vascular endothelium is required for the investigation of its association with atherosclerosis." (PMID 38255895, 2024). "Moreover, increased miR-140-5p elevated ROS levels causing oxidative stress by Nrf2/Sirt2/Keap1/HO-1 pathway in mice with atherosclerosis." (PMID 35011574, 2021). "Also, E2-induced H2S protects against atherosclerosis by upregulating Kelch-like ECH-associated protein 1 (Keap1) expression and inhibiting VSMC calcification and by downregulating MMP-2 and α5β1 integrin expression and inhibiting VSMC proliferation/migration and vascular inflammation." (PMID 40507889, 2025). "Our study identified Sirt7 as a key modulator of Keap1 acetylation and Nrf2 activation, suggesting its therapeutic potential for vascular aging pathologies, such as atherosclerosis and vascular calcification." (PMID 40225574, 2025). "Competitive binding to KEAP1 via Arg483 to inhibit macrophage pyroptosis has been demonstrated in the protection of quercetin anti-atherosclerosis." (PMID 38229085, 2024). "The Kelch-like ECH-associated Protein 1 (KEAP1)/NRF2 antioxidant defence pathway enables cells to counter oxidative and nitrosative stress in atherosclerosis and ischemia/reperfusion injury." (PMID 38372426, 2024). "Systemic Xc- is activated by the Nrf2-Keap1 pathway, and either increased expression of Nrf2 or decreased expression of Keap1 improves the resistance of ferroptosis in atherosclerosis." (PMID 37791060, 2023). "We found that phytochemicals such as sulfur-containing compounds, polyphenols, and terpenoids can modulate the development of atherosclerosis, a key pathological change in the process of CVD caused by BRCA mutations, by mediating Keap1-Nrf2, free radicals, and LDL." (PMID 36569329, 2022). "MCL suppressed atherosclerosis by inhibiting macrophage ferroptosis via activating NRF2 pathway, the related mechanism is through binding to the Arg483 site of KEAP1 competitively." (PMID 38100883, 2024). "Furthermore, in vivo experiment showed that, the atherosclerosis and ferroptosis protective effects of MCL were eliminated in ApoE−/− mice with KEAP1-R483S injection." (PMID 38100883, 2024). "MCL suppressed atherosclerosis by inhibiting macrophage ferroptosis by improving oxidative stress, and the related mechanism is to promote NRF2 activation through binding to the Arg483 site of KEAP1 competitively." (PMID 38100883, 2024).
Hyperglycemia (30 papers, 2017 to 2025). An increased concentration of glucose in the blood. "Last, hyperglycemia induces impairment of the Nrf2/Kelch-like ECH-associated protein 1 (Keap1) pathway." (PMID 38255895, 2024). "Most recently, we showed that Kelch-like ECH-associated protein 1 (KEAP1):nuclear factor erythroid-derived 2-related factor (Nrf2) complex plays a central role in defending beta cells from the adverse effects of hyperglycemia-induced oxidative stress in high-fat diet–fed Zucker rats." (PMID 36632484, 2022). "Hyperglycemia-mediated mitochondrial dysfunction has been correlated with the overproduction of ROS and impairments in Kelch-like ECH-associated protein 1 (Keap1) and Nuclear Factor (erythroid-derived 2-)-like 2 (Nrf2) mediators in diabetic retinopathies." (PMID 40722945, 2025). "In our study, the NaHS treatment in primary cardiomyocyte cultures subjected to hyperglycemia, HR, or both conditions promoted an increase in the expression of Nrf2 and a decrease in the expression of its regulator Keap1." (PMID 40298815, 2025). "Our in vitro and in vivo studies revealed that hyperglycemia significantly increased Keap1 expression and inhibited Nrf2 and NQO1 expression, whereas PET treatment reversed these trends and improved oxidative stress and ferroptosis." (PMID 41181708, 2025). "Our multilevel investigation demonstrated that PGK1 induction in GDM placentas parallels antioxidant dysfunction, linking hyperglycemia to OS through Keap1-Nrf2 suppression." (PMID 40959277, 2025). "Hyperglycemia induces the production of ROS that oxidize cysteine sequences in the Keap1 protein, which destroys the interaction of Keap1 and Nrf2, leading to the accumulation of Nrf2." (PMID 34249265, 2021). "Growing evidence has been shown that, under stress condition, such as chronic hyperglycemia, Keap1/Nrf2 signaling played a pivotal role in regulating the antioxidant response." (PMID 33479232, 2021). "Summarizing the results, our findings demonstrated that TGF-β1 protected RGCs against hyperglycemia-induced oxidative damage by promoting cell antioxidation and neuroprotection pathways, including Nrf2/Keap1/ALDH3A1/HO-1 signaling." (PMID 32899874, 2020). "Under IR conditions, hyperglycemia plays a significant role in inducing Nrf2 degradation in the liver by upregulating Keap1 or through activating other non-Keap1 degradation pathways such as glycogen synthase kinase 3 (GSK3), which induces phosphorylation-mediated degradation of Nrf2." (PMID 40869259, 2025). "This suggests chronic hyperglycemia may override canonical oxidative stress responses, potentially through KEAP1-independent degradation pathways or epigenetic silencing of Nrf2 transcription." (PMID 40529489, 2025). "However, hyperglycemia, oxidative and inflammatory stress in our model increased the mRNA levels of Nrf-2, Keap1, and HO-1; the increased Nrf-2 might be due to increased de novo synthesis." (PMID 36401276, 2022). "In addition, conventional MD and GaMD simulations supported the hypothesized mechanism whereby PHL protected cardiomyocyte from hyperglycemia through disruption of the interaction between Keap1 and Nrf2." (PMID 30619098, 2018). "Here, we show that hyperglycemia-induced oxidative stress and ER stress increased the expression of p-PERK in STZ-induced DPN rats, promoted the dissociation of Nrf2 from Keap1 to induce the expression of HO-1, γGCS, GST and NQO1." (PMID 28432299, 2017). "Interestingly, Keap1 was increased by hyperglycemia, but PHL downregulated Keap1 protein levels." (PMID 30619098, 2018).
liver cancer (29 papers, 2013 to 2025). An epithelial or non-epithelial malignant neoplasm that arises from the liver. "By interfering with the Nrf2 binding site and preventing it from binding to Keap1, it can alter the expression of kelch-like ECH-associated protein-1 (Keap1), a liver cancer factor, and increase the expression of essential antioxidative signals like HO-1." (PMID 40569949, 2025). "Mutations in the KEAP1 gene, causing destabilized Nrf2/Keap1 relation and excessive Nrf2 activity, are associated with occurrence and chemoresistance in leukemia, lung, breast, colon, gastric, and liver cancer." (PMID 35664671, 2022). "Little is known about the role of mutations in the Nrf2/ Keap1 pathway in the development of liver cancer due to the limited research on the development of HCC." (PMID 34202320, 2021). "In addition, xanthine oxidoreductase (XOR) can interact with USP15 to enhance the stability of Kelch-like ECH-associated protein 1 (KEAP1), which ultimately promotes the accumulation of reactive oxygen species (ROS) and liver cancer stem cells (CSCs)." (PMID 35875077, 2022). "Keap1–Nrf2 dysregulation via mutation in either Nrf2 or its inhibitor Keap1 has been associated with the initiation of various tumors, including adenocarcinoma, and gall bladder and liver cancers." (PMID 29662489, 2018). "In liver cancer cell lines, p62 can bind to Keap1 and disrupts the interaction of Keap1 with Nrf2 when exposed to compounds inducing iron toxicity." (PMID 37025659, 2023). "Lung, ovarian, gallbladder, and liver cancers are known to have defects in Keap1 that result in Nrf2 over-activation." (PMID 34316328, 2021). "Lung, ovarian, gallbladder, and liver cancers are known to have defects in Keap1, leading to Nrf2 over-activation." (PMID 34316328, 2021). "Recently, p62 has been reported to compete Keap1 biding with Nrf2 in sorafenib resistant liver cancer cells, leading to an increase in the transcription of antioxidant genes to inhibit ferroptosis." (PMID 32751249, 2020). "Coordinated overexpression of Ogg1 and Nrf2 and downregulation in Keap1 expression were previously shown in HepG2 human liver cancer cell line after the menadione and H2O2/Fe2+ exposure." (PMID 28785378, 2017). "Somatic mutations that impair the function of KEAP1 and lead to the constitutive stabilisation of NFE2L2 have been found in lung, gallbladder and liver cancer in humans." (PMID 23724128, 2013). "Mutations that target the Nrf2/Keap1 regulatory pathway are not just associated with lung and liver cancer." (PMID 34202320, 2021). "In liver cancer cells, ferroptosis activators (e.g., erastin, sorafenib) could enhance the expression of SQSTM1/p62 (sequestosome 1), a competitive inhibitor of KEAP1 (Kelch-like ECH-associated protein 1)." (PMID 32103754, 2020). "Liver hepatocellular carcinoma (LIHC) is the most common type of liver cancer, but there is a lack of effective indicators for its early diagnosis and prognosis, so we explored the role of KEAP1 in LIHC patients in this study." (PMID 38938386, 2024). "This study reveals that DPP9 inhibits ubiquitin-mediated degradation of NRF2 protein by binding to KEAP1, up-regulates NRF2 protein levels, promotes mRNA transcription of NQO1, inhibits intracellular ROS levels, and thus weakens the responses of liver cancer to chemotherapy drugs." (PMID 39094401, 2024). "In liver cancer, the KRAL/miR-141/Keap1 network was shown to reverse 5-FU resistance." (PMID 33869020, 2021).